CRP (C-reactive protein)
Diseases named in the same sentence as CRP in open-access papers (continued):
Sharing a sentence is not in itself a finding about the gene and the disease.
COVID-19 (continued). "The hypothesis is that patients with moderate/severe COVID-19 have a local sub-inflammatory status that could remain localized in the vasculature, responsible for persisting endothelial dysfunction in the middle-term, and not inducing systemic production of CRP." (PMID 37626735, 2023). "In non-COVID-19, DPP3 was significantly correlated with CRP (ρ = 0.35, p < 0.05), as opposed to IL-6 and leucocytes (each p = n.s)." (PMID 37733154, 2023). "IL-6, LDH, CRP and PCT levels were significantly higher in non-survivor hospitalized patients affected by COVID-19, representing not only markers of inflammation but also in-hospital mortality." (PMID 36836679, 2023). "CRP and NLR are good predictors of disease severity and mortality in patients with COVID-19 as well as of bacteraemia in patients without COVID-19." (PMID 37939245, 2023). "In a Brazilian COVID-19 cohort, the levels of ESR were higher in the no-survival, requiring intensive unit care; ESR correlates with WBC, lymphocytes, and CRP." (PMID 37372959, 2023). "On the other hand, the blood test results that were considered in the final model were primarily taken in subjects admitted during the first waves of COVID-19, but currently, parameters such as IL6 and CRP are not routinely collected at admission." (PMID 36835788, 2023). "When patients with COVID-19 and liver cirrhosis were excluded, plasma PCSK9 did not correlate with the CRP, leukocyte count, or procalcitonin." (PMID 37515197, 2023). "CRP and SAA are plasma proteins that, to the best of our knowledge, have only been detected in platelets in a proteomic analysis of platelets from COVID-19 platelets but not in any other context." (PMID 37681923, 2023). "As reported by others, CRP, IL6, IL1β, but not TGFβ levels increased in patients with more severe stages of COVID-19." (PMID 38313435, 2023). "The positive patients and those who had symptoms but negative COVID-19 reports were followed by high-resolution computed tomography (HRCT) (52%) and C-reactive protein (CRP) testing (45%) to ensure that no COVID-19 infection was missed." (PMID 38090450, 2023). "CRP and CLR (CRP to lymphocyte ratio) among the outpatient, inpatient without IMV, and inpatient with IMV COVID-19 groups were (7.91 vs 52.45 vs 69.95) and (11.49 vs 59.87 vs 201.76), respectively." (PMID 37903087, 2023). "Consistent with our findings, it has been observed in a sepsis cohort that includes COVID-19 that there is a positive correlation between PCSK9 and CRP, but not with WBC and PCT." (PMID 37904138, 2023). "In the group of patients post-COVID-19 without pulmonary fibrosis, DLCO corr values (%) and distance covered in the 6-minute walk test significantly correlated with inflammatory marker CRP." (PMID 38256314, 2023). "However, males with COVID-19 from our cohort had significantly higher CRP levels compared to females, even though they were no more likely to die than their female counterparts, providing evidence that their higher CRP levels were not related to their hospitalization outcomes." (PMID 38003780, 2023). "Additionally, patients exhibiting increased levels of NLR, CRP, LDH, ferritin, and procalcitonin during acute infection may benefit from boosting effect on the SARS-CoV-2 IgG concentration even with a single dose of COVID-19 vaccine after 3 months of infection." (PMID 37293303, 2023). "The time from SARS-CoV-2 infection’s onset to hospital admission does not seem to influence the prognostic value of CRP, IL-6, and NLR in non-severe COVID-19." (PMID 36831898, 2023). "In light of the results of this study, the time from symptoms’ onset to reporting to the medical facility does not influence the prognostic value of CRP, IL-6, and NLR in initially non-severe COVID-19 patients." (PMID 36831898, 2023). "DPP3 was significantly increased in COVID-19 patients compared to those without SARS-CoV-2 (p < 0.001), opposite to IL-6 and CRP (each p = n.s.)." (PMID 37733154, 2023).
COVID-19 (continued). "While the levels of pro-inflammatory markers, such as CRP, IL-6, IL-1Ra, and TNF-α, were slightly higher, and anti-inflammatory cytokines, such as TGF-β1, were lower in COVID-19/PLWH than in those without HIV, none of these differences was significant." (PMID 37646024, 2023). "Mechanically ventilated COVID-19 patients with and without SSC-CIP had comparable initial inflammation levels on admission, as indicated by C-reactive protein (CRP), procalcitonin (PCT), interleukin-6 (IL-6), and ferritin." (PMID 37119516, 2023). "The clinical chemistry data showed a significant elevation of inflammatory biomarkers including C-reactive protein (CRP) and procalcitonin (PCT), but not interleukin 6 (IL-6) in the COVID-19 group compared to the non-COVID-19 group." (PMID 37386635, 2023). "Both CRP and LDH have been reported as prognostic markers of deterioration in patients with COVID-19 including mild/non-severe cases as well." (PMID 36969618, 2023). "A non-peer-reviewed study of 375 COVID-19 patients identified LDH and CRP thresholds (LDH < 365 U/L; high-sensitivity (hs) CRP < 41.2 mg/L) that reliably predicted a favorable prognosis." (PMID 37048652, 2023). "While PLS-DA did not completely separate PIMS-TS from acute COVID-19 patients, variable importance projection (VIP) analysis showed that CRP elevation and reduced platelet numbers were more pronounced in PIMS-TS as compared to acute COVID-19 patients." (PMID 38027272, 2023). "Plasma Gal-9 shows positive correlations with proinflammatory mediators, especially IL-6, IP-10, and CRP, and a negative correlation with an anti-inflammatory cytokine, transforming growth factor-β (TGF-β), in COVID-19 patients." (PMID 36835000, 2023). "Antibiotics use in this study was highly correlated with high admission CRP and white cell count (WCC), indicating that AKI has occurred due to COVID-19 or co-infection rather than the nephrotoxic effects of antibiotics." (PMID 37162791, 2023). "Our research showed that non-surviving hospitalized COVID-19 patients had significantly higher PCT, CRP, LDH and IL-6 levels, which are indicators of both in-hospital mortality and inflammation." (PMID 36836679, 2023). "After assessing non-cytokine markers of inflammation in COVID-19 patients (POP2), we found that for every 1-point increase in ESR, CRP, and WBC, there was statistical worsening in ventilation, ICU admission, and mortality (ESR not significant)." (PMID 36589196, 2022). "CRP, LDH and fibrinogen were the three parameters with the highest AUC for prediction of critical vs. non-critical COVID-19." (PMID 35407418, 2022). "A number of proteins identified as outcome predictors have also been shown to be differentially expressed in sepsis, including SAA1, CRP, SERPINA1, KLKB1, and A2M, indicating a general inflammatory signature rather than specific markers of COVID-19." (PMID 36812516, 2022). "Differences in CRP, ALT, AST and LDH levels were observed between severe and non-severe COVID-19 groups." (PMID 36429772, 2022). "However, these rates may be overestimated, as the clinical and biological signs of co and secondary infection, such as fever and CRP, are also elevated in COVID-19 without infectious complications, making the differential diagnosis between simple colonization and infection difficult in this context." (PMID 35740112, 2022). "Available data provide evidence for the differentiation of severe and non-severe cases of COVID-19 based on inflammatory biomarkers including lactate dehydrogenase (LDH), C-reactive protein (CRP), and lymphocyte count." (PMID 36109825, 2022). "C-reactive protein (CRP), lactate dehydrogenase (LDH), the platelet-to-lymphocyte ratio (PLR) and the NLR are significantly higher in COVID-19 patients compared to patients who do not have COVID-19." (PMID 36556258, 2022).
COVID-19 (continued). "In previous studies, WBC, lymphocyte, procalcitonin, CRP, D-Dimer, CK, CKMB, and troponin levels in patients with severe pneumonia due to COVID-19 differed compared to non-serious patients." (PMID 35957846, 2022). "There were significant differences in comorbidity, presence of pleural thickening, CRP increase, abnormal WBC and lymphocytes counts between severe and non-severe patients with COVID-19 in both primary and validation cohorts." (PMID 35078525, 2022). "Correlations between Age, Gender, D-dimer value, CRP value, with Mortality for the combined dataset of ICU and non-ICU COVID-19 patients." (PMID 36568370, 2022). "From the present study, there were significant differences in lymphocytes, NLR, CRP, AST, Cr, CD3+ T cells, CD4+ T cells, CD8+ T cells, CD19+ T cells, and CD16+/CD56+ NK cells in mild/moderate COVID-19 cases with and without progression." (PMID 35619076, 2022). "Height, age, PBW, FiO2, PaO2, Horowitz index, PCT, and CRP values on ICU admission were found to be similar in both groups (namely puerperant and non-pregnant COVID-19 patients)." (PMID 36254075, 2022). "A detailed comparison of laboratory biomarkers between COVID-19 patients with and without pneumonia indicated an increased level of neutrophil, procalcitonin, ESR, CRP, AST, D-dimer, LDH, severe cough, chest pain, and severe sweating in pneumonia patients." (PMID 35997388, 2022). "CRP levels were higher in patients with COVID-19 than non-COVID-19 patients (p = 0.001), and PCT levels were lower in patients with COVID-19 than non-COVID-19 patients (p = 0.011)." (PMID 34493032, 2022). "The biological workup showed an increase in CRP with elevated D-dimer, but no abnormalities in cardiac markers, including troponin and BNP, the COVID-19 testing was negative and absence of thrombocytopenia." (PMID 35784614, 2022). "In determining the severity of COVID-19 progression, initial non-cytokine markers, particularly ferritin, ESR, CRP, and WBC were the strongest predictors of disease severity." (PMID 36589196, 2022). "In contrast, lower levels of absolute lymphocyte count (ALC) and higher levels of CRP, D-dimer, and absolute neutrophil count (ANC) were observed in patients with MIS-C compared to non-severe COVID-19." (PMID 36295088, 2022). "Since serum CRP and IL-6 are natively elevated in NAFLD patients, increased levels in COVID-19 are not an unexpected finding." (PMID 35743825, 2022). "C-reactive protein (CRP) and white blood cell (WBC) count were the most consistent non-cytokine predictors of COVID-19 severity." (PMID 36589196, 2022). "Median CRP was 1.2 (0.7–2.1) mg/L, with only one value above the ULN (10 mg/L) in a patient identified as having acute COVID-19 pneumonitis, in spite of negative PCR prior to attending DCRS." (PMID 35687603, 2022). "In our study, we confirmed higher levels of inflammatory markers—C-reactive protein and IL-6—in critically ill COVID-19 patients compared to non-ICU COVID-19 patients." (PMID 34071149, 2021). "Although CRP elevation and lymphopenia were not specific for COVID-19 severity and mortality assessment, CLR was found more useful than CRP or lymphocytes when considered separately." (PMID 34945746, 2021). "COVID-19 positive patients had lower PON1 activities and galectin-3 concentrations, and higher PON1, CRP, IL-10, and ACE2 concentrations than COVID-19 negative patients." (PMID 34205807, 2021). "As expected, our comparison of hospitalized and non-hospitalized COVID-19 patients found significantly higher LDH, CRP, PCT, and troponin T (TNT) concentrations and lower estimated glomerular filtration rates (eGFRs) among the COVID-19 inpatients." (PMID 34960725, 2021). "Confirming such link in COVID-19 is even more important since this result is contrary to what was previously reported in non-COVID-19 ARDS, in which the increase in CRP is thought to be protective instead." (PMID 34506514, 2021).
COVID-19 (continued). "Interestingly, the C-reactive protein (CRP) negatively correlated with LDL-C (p = 0.013) and HDL-C, even if at the limit of statistical significance with p = 0.05, suggesting that the lipid profile lowering could follow the rising of the inflammatory state typical of COVID-19." (PMID 34440605, 2021). "CRP, while not a SARS-CoV-2 positive test, had prognostic value in the total population of patients presenting with COVID-19-related symptoms." (PMID 35011944, 2021). "CRP and LDH were also found to be statistically lower in COVID-19 patients compared to other groups except for other non-pneumonia infections." (PMID 34244563, 2021). "For example, COVID-19 patients taking ACE/ARBs had lower levels of inflammatory markers, such as interleukin 6 (IL-6), C-reactive protein (CRP) and procalcitonin, than those not taking these drugs." (PMID 34090358, 2021). "LDH, CRP and ALB are useful prognostic marker for predicting nucleic acid turn negative within 14 days in symptomatic patients with COVID-19." (PMID 33663273, 2021). "In previous studies, patients with severe COVID-19 and nonsurvivors had significantly higher NLR, PLR, SII, and CRP/Alb ratio values, but lower PNI values." (PMID 34900028, 2021). "Vitamin D showed a significant negative correlation with LDH, CRP, ESR, ferritin, and D-dimer, which was the most reliable predictor of COVID-19 severity in T1DM patients." (PMID 34840966, 2021). "Although CRRT did not improve the survival of critical COVID-19 patients with CRS, some inflammatory markers such as the CRP, D-dimer, WBC counts, and neutrophil counts decreased significantly after CRRT." (PMID 33811755, 2021). "Indeed, CRP levels have been correlated with white matter lesions in multiple pathologies not related to COVID-19, such as cerebral small vessel disease, neurodegenerative processes and obesity, which may occur as comorbidities in COVID-19 encephalopathy patients." (PMID 34709472, 2021). "Lastly, in our cohort, there was a significant difference in laboratory biomarkers (CRP, LDH, lactate) in patients with abnormal CXR compared to patients without chest infiltrates, only among the patients with COVID-19." (PMID 34692325, 2021). "C-reactive protein (CRP) which, in other settings, is widely used as a biomarker of bacterial infection, appears to reflect severity of illness and prognosis in COVID-19, irrespective of the presence of additional bacterial infection." (PMID 34062898, 2021). "It was a multicenter, open-label, Bayesian trial nested within the CORIMUNO-19 cohort, in patients with moderate-to-severe COVID-19, neither receiving mechanical ventilation nor admitted at ICU, and with a CRP >25 mg/L." (PMID 34659200, 2021). "In this study, COVID-19 patients showed elevated LDH, ferritin, and CRP levels compared to the suspected non-COVID-19 group." (PMID 33861750, 2021). "Tocilizumab also decrease inflammatory markers such as C-reactive protein (CRP) and D-dimer in 54 patients with severe COVID-19, although the mean reduction in these biomarkers did not significantly influence outcome." (PMID 34287285, 2021). "In this study, we retrospectively analyzed the clinical data of symptomatic patients with COVID-19, logistic regression analysis revealed patients whose nucleic acid turned negative within 14 days had lower LDH, CRP and higher ALB." (PMID 33663273, 2021). "Blood test performed by day-5 of symptoms onset showed that mean values of CRP, NLR, LDH and CK were significantly higher compared with patients not experiencing progression of COVID-19." (PMID 34454452, 2021). "An observational study that included 39 COVID-19 patients with STEMI showed higher levels of troponin T and lower lymphocyte count, but elevated D-dimer and C-reactive protein compared to patients without COVID-19." (PMID 34829920, 2021). "In the present study, the ROC curve was used to analyze the specificity and sensitivity of different CRP and NLR values in severe and non-severe COVID-19 patients." (PMID 33244379, 2020).
COVID-19 (continued). "Elevation of CRP, LDH, D-dimer and lymphopenia were all frequently observed but only CRP and LDH were significantly higher in confirmed COVID-19 patients as compared with non-confirmed ones." (PMID 32824683, 2020). "Compared to COVID-19 patients without CVD, C-reactive protein (CRP), troponin I (TnI), and serum creatinine were significantly increased in COVID-19 patients with CVD." (PMID 32765943, 2020). "Compared with the non-CVD group, COVID-19 patients in the CVD group were older and had higher levels of TnI, CRP, and creatinine." (PMID 32765943, 2020). "Lack of recent paraclinical findings in favor of COVID-19 (Specific COVID-19 tests) or non-specific tests such as CBC, CRP, LDH." (PMID 33123320, 2020). "Other tests, including liver function, lactate dehydrogenase, inflammatory markers such as C-reactive protein (CRP), and procalcitonin, were unable to distinguish COVID-19 and non-COVID-19 cases in our PUI cohort." (PMID 32931517, 2020). "The foreign package of the R language was used to read the original data, and the rms package was used to bring age, CHD, Lym%, PLT, CRP, LDH and D-dimer into the functional model, and form the nomogram model for predicting the outcome of COVID-19 patients." (PMID 33256643, 2020). "Moreover, patients with MIS typically present very high levels of circulating inflammatory biomarkers (C-reactive protein [CRP], IL-6, ferritin), generally higher compared to those found in patients with COVID-19 without MIS." (PMID 39775145, 2025). "Regardless of clinical outcome, patients in our COVID-19 cohort showed limited differences in most serum inflammatory markers, although the mean or median values of several markers, such as TNFα, ICAM-1, CRP, AAT, and ferritin, were higher in more severe patients." (PMID 38494528, 2024). "Counts of lymphocytes, neutrophils, platelets, NMR, NLR, D-dimer, interleukin-6, CRP levels, and lactate dehydrogenase (LDH) levels may be able to help differentiate between severe and non-severe COVID-19." (PMID 39723295, 2024). "In both admission and follow-up evaluation, a more significant association was observed with CRP-related inflammatory biomarkers such as CRP/albumin ratio and CRP/lymphocyte ratio rather than NLR and PLR, which are widely used in the literature, in showing the severity of COVID-19." (PMID 38298278, 2024). "Additionally, patients with severe COVID-19 exhibited a significantly reduced peripheral blood monocyte count, in contrast to increased levels of NLR, SAA and CRP, as compared to the non-severe group (all p<0.05)." (PMID 39679195, 2024). "In both admission and follow-up evaluation, a more significant association was observed with CRP-related biomarkers such as CRP/albumin ratio and CRP/lymphocyte ratio rather than NLR and PLR, which are widely used in the literature, in showing the severity of COVID-19." (PMID 38298278, 2024). "The results of CRP, suPAR, and the increased incidence of AKI could even be interpreted as an indication of the damaging influence of sevoflurane in COVID-19-related acute lung injury, even if the study has not been powered for these endpoints." (PMID 38536545, 2024). "However, the observation frequency of CRP, AAT, FGA, S100, SAA1 and others was often greater in ICU-ARDs or COVID-19 compared to normals, therefore these proteins were not specific markers of COVID-19 infection but rather reflected lung damage." (PMID 37031181, 2023). "A small retrospective study on 52 ICU and 47 no-ICU COVID-19 patients indicated that PCT and CRP may be useful in identifying secondary bacterial infections and guiding the use of antibiotics." (PMID 37887237, 2023). "However, WBC, Neutr, Lymph, PLT, D-dimer, CRP, PCT, CK, AST, ALT, Cr, and LDH levels were not relevant indicators for severity assessment of pediatric patients with COVID-19 in this study." (PMID 37497300, 2023).